RNU6-983P (RNA, U6 small nuclear 983, pseudogene)
Gene: Small nuclear RNA gene on chromosome 1 (194,488,103 to 194,488,205, reverse strand). Ensembl gene ENSG00000251813.
Homologues: Orthologues: chimpanzee U6 (99% identical), macaque U6 (83% identical), guinea pig U6 (74% identical), mouse Gm54442 (64% identical), dog U6 (62% identical), mouse Gm54479 (57% identical). Paralogues in human: RNU6-106P (79% identical), RNU6-1152P (79% identical), RNU6-434P (79% identical), RNU6-480P (79% identical), RNU6-1031P (78% identical), RNU6-16P (78% identical), RNU6-20P (78% identical), RNU6-211P (78% identical), RNU6-21P (78% identical), RNU6-46P (78% identical), RNU6-728P (78% identical), RNU6-80P (78% identical), and 1289 more.